KIF2A (kinesin family member 2A)
Description:
Plus end-directed microtubule-dependent motor required for normal brain development. May regulate microtubule dynamics during axonal growth. Required for normal progression through mitosis. Required for normal congress of chromosomes at the metaphase plate. Required for normal spindle dynamics during mitosis. Promotes spindle turnover. Implicated in formation of bipolar mitotic spindles. Has microtubule depolymerization activity.
Synonyms: hK2; KIF2; CDCBM3
Tractability: Small molecule: a structure with a bound ligand is known. PROTAC: ubiquitination databases record sites on it; its protein half-life has been measured.
Gene: Protein-coding gene on chromosome 5 (62,306,162 to 62,391,025, forward strand). Ensembl gene ENSG00000068796.
Subcellular location: Cytoplasm; Cytoplasm, cytoskeleton, microtubule organizing center, centrosome; Cytoplasm, cytoskeleton, spindle pole; Cytoplasm, cytoskeleton, spindle
Subcellular location (Human Protein Atlas): Annulus; Basal body; Centrosome; Nucleoli; Nucleoplasm; Cytosol; Mid piece; Mitotic spindle; Principal piece
Pathways (Reactome):
Cell Cycle: Amplification of signal from unattached kinetochores via a MAD2 inhibitory signal; EML4 and NUDC in mitotic spindle formation; Mitotic Prometaphase; Resolution of Sister Chromatid Cohesion; Separation of Sister Chromatids
Hemostasis: Kinesins
Immune System: MHC class II antigen presentation
Signal Transduction: RHO GTPases Activate Formins
Vesicle-mediated transport: COPI-dependent Golgi-to-ER retrograde traffic
Gene Ontology:
Molecular function: microtubule binding; protein binding; cytoskeletal motor activity; ATP binding; microtubule motor activity
Biological process: microtubule cytoskeleton organization; mitotic spindle assembly; mitotic spindle organization; regulation of cell migration; microtubule depolymerization; dendritic transport; microtubule-based movement; mitotic sister chromatid segregation
Cellular component: centriolar subdistal appendage; centriole; centrosome; cytoplasm; cytosol; membrane; microtubule; nucleoplasm; spindle microtubule; spindle pole; kinesin complex; spindle; dendrite; GABA-ergic synapse; sperm principal piece
Genetic constraint (gnomAD): Loss-of-function variants: 8 observed, 23.38 expected, observed/expected ratio (o/e) 0.34, 90% interval 0.2 to 0.62. The upper end of that interval is the gene's LOEUF score, 0.62, which puts it in group 2 of 6, group 1 being the genes least tolerant of losing a copy. Missense variants: 170 observed, 291.64 expected, observed/expected ratio (o/e) 0.58, 90% interval 0.51 to 0.66. Synonymous variants: 88 observed, 103.32 expected, observed/expected ratio (o/e) 0.85, 90% interval 0.72 to 1.02.
Homologues: Orthologues: chimpanzee KIF2A (99% identical), macaque KIF2A (99% identical), dog KIF2A (99% identical), pig KIF2A (99% identical), rat Kif2a (99% identical), mouse Kif2a (98% identical), rabbit KIF2A (96% identical), tropical clawed frog kif2a (93% identical), guinea pig KIF2A (88% identical), zebrafish kif2a (80% identical). Paralogues in human: KIF2C (53% identical), KIF2B (52% identical), KIF24 (33% identical), KIF16B (22% identical), KIF1A (22% identical), KIF13B (21% identical), KIF5C (21% identical), KIF13A (21% identical), KIF14 (21% identical), KIF1B (21% identical), KIF5A (21% identical), KIF7 (21% identical), and 29 more.
Diseases named in the same sentence as KIF2A in open-access papers:
KIF2A is named in the same sentence as 62 diseases in open-access papers, as found by Europe PMC text mining. Sharing a sentence is not in itself a finding about the gene and the disease. The quoted sentences say what the papers report.
breast carcinoma (11 papers, 2014 to 2024). "Up-regulated KIF2A, another kinesin-13 family member, and depolymerase was shown to be associated with poor prognosis in patients with lung adenocarcinoma, breast cancer and gastric cancer by promoting tumor growth and migration." (PMID 34830827, 2021). "The increase in KIF2A expression was associated with a decrease in patient survival time indicating that KIF2A is a potential novel prognosis biomarker for breast cancer." (PMID 24950762, 2014). "In this study, we found that the mitotic centromere-associated Kinesin-13 protein KIF2A mRNA and protein levels in breast cancer tissue were highly expressed compared to adjacent normal tissue." (PMID 24950762, 2014). "KIF2A is likely to be an important growth factor and might be associated with the malignant phenotype of breast cancer cells." (PMID 24950762, 2014). "Also, one study reports that KIF2A high expression is correlated with lymph node metastasis and HER2 positive cancer in breast cancer patients, and another study shows that KIF2A high expression is associated with increased pathological grade in glioma patients." (PMID 33331418, 2020). "Studies showed that KIFC1 and KIF2A were both highly expressed in breast cancer and promoted the proliferation and migration of breast cancer cells." (PMID 38713252, 2024). "For example, KIF2A was highly expressed in breast cancer tissue, increased KIF2A indicated a poor OS (OR = 16.55) and lymph node metastasis." (PMID 36798768, 2023). "The stability of the ATIP3/KIF2A/Dda3 molecular complex requires phosphorylation by the mitotic kinase, Aurora A, a major kinase deregulated in cancer, including breast cancer." (PMID 34062782, 2021). "The expression of KIF2A was found to be remarkably higher in breast cancer tissue samples compared with corresponding adjacent tissues." (PMID 28616658, 2017). "Recent studies reported the correlation between KIF2A expression and malignant tumors, including breast cancer, SCCOT, colorectal cancer, and ovarian cancer." (PMID 28616658, 2017). "Studies found that knockdown of KIF2A suppressed the proliferation, migration, and invasion of breast cancer cell line MDA-MB-231 cells and SCCT cell line Tca8113 cells." (PMID 27773961, 2016). "And KIF2A expression in breast cancer tissue with lymph node metastasis and HER2 positive cancer was higher than that in cancer tissue without." (PMID 27773961, 2016). "We evaluated the KIF2A expression and other clinicopathologic factors on prognosis of breast cancer by univariate analyses." (PMID 24950762, 2014). "The high expression of KIF2A (OR: 16.55, 95% CI: 2.216-123.631) in breast cancer tissue was an independent prognostic factor for breast cancer in addition to the patient’s tumor histological grade (OR: 3.108, 95% CI: 1.712-5.643)." (PMID 24950762, 2014). "In the current study using MDA-MB-231 breast cancer cell, we found that upon transfection with KIF2A-siRNA, cell proliferation was inhibited, as was cell migration and invasion." (PMID 24950762, 2014). "Immunohistochemical staining, real time RT-PCR and western blot were used to examine the expression of KIF2A in cancer tissues and adjacent normal tissues from breast cancer patients." (PMID 24950762, 2014). "We detected the KIF2A mRNA and protein levels in 12 paired primary breast cancer tissues and the corresponding adjacent normal tissues using real time RT-PCR and western blotting, respectively." (PMID 24950762, 2014). "The IHC results showed that 80 of 120 (67%) cases of breast cancer overexpressed KIF2A compared with the paired normal adjacent tissues." (PMID 24950762, 2014). "The KIF2A expression in relation to the key clinico-pathologic factors of breast cancer, such as age, tumor size, tumor histological grade, clinical stage, ER, PR and HER2 status, was examined in the 120 patients using univariate and multivariate analysis." (PMID 24950762, 2014).
breast carcinoma (continued). "KIF2A mRNA was up-regulated in primary breast cancer tissue, by 2.95 fold the expression in adjacent normal breast tissues (P < 0.001)." (PMID 24950762, 2014). "The goal of this study was to explore the function of KIF2A in human breast cancer, and to determine its effects on the proliferation and invasion of breast cancer cells." (PMID 24950762, 2014). "Patients with high KIF2A expression in breast cancer tissues or adjacent normal tissues were more likely to have significantly poor survival (P = 0.002 when high KIF2A in cancer tissues, and P = 0.024 when in adjacent tissues)." (PMID 24950762, 2014). "Prior studies demonstrated that overexpression of KIF2A may be involved in the carcinogenesis of breast cancer, squamous cell carcinoma of the oral tongue (SCCOT), colorectal cancer, and ovarian cancer." (PMID 28616658, 2017). "A recent study explored the function of KIF2A during breast cancer development and progression." (PMID 28616658, 2017). "IHC was performed to determine KIF2A protein expression in 120 primary breast cancer tissues." (PMID 24950762, 2014). "In addition, multivariate analysis indicated that KIF2A was an independent prognostic for outcome in breast cancer (OR: 16.55, 95% CI: 2.216-123.631, P = 0.006)." (PMID 24950762, 2014). "KIF2A may play an important role in breast cancer progression and is potentially a novel predictive and prognostic marker for breast cancer." (PMID 24950762, 2014). "The role of KIF2A during breast cancer tumorigenesis and progression was studied." (PMID 24950762, 2014). "For instance, KIF2A expression has been reported to negatively correlate with OS and be an independent predictive factor for OS in DLBCL, breast cancer, as well as epithelial ovarian cancer patients." (PMID 33331418, 2020). "Emerging evidence has revealed that KIF2A is overexpressed in tissue samples of several malignancies, such as diffuse large B cell lymphoma (DLBCL), breast cancer, and lung squamous cell carcinoma." (PMID 33331418, 2020). "Furthermore, the downregulation of KIF2A resulted in significant reduction of both cell growth and tumor migration and invasion, suggesting that KIF2A overexpression by breast cancer cells may alter key behaviors of tumor cells and lead to aberrant proliferation and metastasis." (PMID 28616658, 2017). "However, the role of KIF2A in breast cancer remains unknown." (PMID 24950762, 2014). "Breast cancer cell line, MDA-MB-231 was used to study the proliferation, migration and invasion of cells following KIF2A-siRNA transfection." (PMID 24950762, 2014). "A few studies have shown that KIF2A is overexpressed in tumor tissues and correlates with clinicopathological features in patients with some cancers (such as diffuse large B cell lymphoma (DLBCL), breast cancer, and lung squamous cell carcinoma)." (PMID 33331418, 2020). "Analysis of gene expression data of various gene expression synthesis (GEO) datasets for breast cancer using genetic algorithms and bioinformatics tools showed that FAM134B combined with KIF2C, ALCAM, and KIF2A may identify certain subtypes of breast cancer." (PMID 33199694, 2020). "A negative correlation was found between KIF2A expression levels in breast cancer and the survival time of breast cancer patients (P < 0.05)." (PMID 24950762, 2014). "Consistently, the western blotting analysis showed that the KIF2A protein levels in primary breast cancer tissues were markedly higher than those in the adjacent normal breast tissues (P < 0.001)." (PMID 24950762, 2014).
glioma (9 papers, 2016 to 2025). A benign or malignant brain and spinal cord tumor that arises from glial cells (astrocytes, oligodendrocytes, ependymal cells). "Researchers had proved that KIF2A served as an oncogene in a series of tumors, such as nasopharyngeal carcinoma, lung adenocarcinoma, gastric cancer, and glioma." (PMID 35164763, 2022). "In conclusion, circHIPK3 promoted glioma development as well as drug resistance through the miR-524-5p/KIF2A and miR-421/ZIC5 regulatory axes." (PMID 36606192, 2022). "The results showed that circHIPK3 knockdown increased TMZ sensitivity in glioma and affected proliferation, apoptosis, and metastasis via the miR-524-5p/KIF2A-mediated PI3K/AKT pathway." (PMID 35071748, 2022). "It was recently demonstrated that expression levels of KIF2A were significantly higher in grades III-IV glioma tissues compared with those in grades I-II glioma tissues." (PMID 27773961, 2016). "It was shown that KIF2A silencing could suppress migration and metastasis of glioma cells, while KIF2A knockdown could stimulate apoptosis in vitro." (PMID 35071748, 2022). "CircHIPK3 was upregulated in glioma, which could enhance the temozolomide resistance of glioma by miR-524-5p/KIF2A axis." (PMID 34407841, 2021). "This facilitates glioma progression and resistance through up-regulating an M-type nonmotile microtubule depolymerase, kinesin family member 2A (KIF2A), expression through activating the PI3K/AKT pathway." (PMID 39877636, 2025). "The suppression of KIF2A could enhance TMZ sensitivity and apoptosis to inhibit the proliferation and development of TMZ-resistant glioma cells, and the silencing of circHIPK3 also had the same effects." (PMID 36606192, 2022).
ovarian carcinoma (8 papers, 2016 to 2022). A malignant neoplasm originating from the surface ovarian epithelium. "KIF2A mRNA contains two binding sites for miR-206, which inhibits the proliferation, migration, and invasion of ovarian cancer cells, and induces apoptosis." (PMID 34659572, 2021). "Our recent study established that KIF2A, a protein suppressed by miR‐206, is relevant in the poor prognosis of ovarian cancer." (PMID 32638511, 2020). "Recently, several reports have shown that aberrantly expressed KIF2A is detected in several cancers, including breast, oral, colorectal, and ovarian cancers, and its expression contributes to cancer cell malignancies." (PMID 30813343, 2019). "In human epithelial ovarian cancer, overexpression of KIF2A was found in tumor tissues, and KIF2A conferred increased invasive and metastatic potential to tumor cells." (PMID 28616658, 2017). "We hypothesized that aberrant KIF2A and HER2-neu expression might be associated with aggressive behavior of epithelial ovarian cancer (EOC)." (PMID 26937910, 2016). "The expression of CXCL5 and KIF2A was upregulated in various cancer tissues, including cervical cancer; additionally, the expression of RGS18 in the tissues of patients with ovarian cancer was also upregulated." (PMID 34827689, 2021). "PCR results showed higher expression of KIF2A mRNA in ovarian cancer samples than in noncancerous tissues (all P < 0.05)." (PMID 26937910, 2016). "Interestingly, high KIF2A and HER2-neu coexpression (KIF2AH/HER2-neuH) were only detected in EOC patients, and none of normal ovarian or fallopian tissues had KIF2AH/HER2-neuH staining, although not all ovarian carcinoma show coexpression of KIF2A and HER2-neu." (PMID 26937910, 2016).
gastric cancer (7 papers, 2014 to 2022). A primary or metastatic malignant neoplasm involving the stomach. "Kinesin family member 2A (KIF2A) induces gastric cancer (GC) growth and invasion, while its clinical relevance in GC patients is not reported." (PMID 35313389, 2022). "This study aimed to explore the linkage of KIF2A with clinicopathological features and prognosis, then investigate its effect on the chemosensitivity in gastric cancer." (PMID 35313389, 2022). "In this study, we aimed to evaluate the expression of KIF2A and its robustness and potential to predict clinical outcomes in gastric cancer (GC) patients." (PMID 27773961, 2016). "Furthermore, KIF2A appears to activate the PI3K/Akt signaling pathway in lung cancer and gastric cancer." (PMID 36447525, 2022).
microcephaly (7 papers, 2016 to 2024). A congenital or acquired developmental disorder in which the circumference of the head is smaller than normal for the person's age and sex. "In humans, single de novo missense mutations in KIF2A were found in patients with early-life epilepsy, posterior pachygyria, microcephaly, and partial agenesis of corpus callosum." (PMID 36733270, 2022). "Here, we present a novel kif2a knock-out zebrafish model, showing hypoactivity, habituation deficits, pentylenetetrazole-induced seizure susceptibility and microcephaly, as well as neuronal cell proliferation defects and increased apoptosis." (PMID 34404749, 2021). "We generated a novel kif2a loss-of-function model in zebrafish and demonstrated that Kif2a deficiency was associated with behavioral alterations, habituation deficits, enhanced susceptibility to seizures, microcephaly, neuronal cell proliferation defects, and increased apoptosis." (PMID 34404749, 2021). "For instance, microcephaly has been associated with mutations in RAB3GAP/RAB18, ARFGEF2, ARF1, kinesin KIF2A, or dynein heavy chain, all affecting both membrane trafficking and neuronal morphogenesis." (PMID 39115595, 2024). "In humans, single de novo mutations in KIF2A are associated with MCD with epileptic seizures, posterior pachygyria, microcephaly, and partial agenesis of corpus callosum." (PMID 36733270, 2022). "KIF2A+/H321D KI mice survived and displayed microcephaly and neuroanatomical anomalies like hippocampal structure abnormalities and cortical layer disorganization, resulting from abnormal neuronal migration and increased cell death." (PMID 34404749, 2021). "It has been reported that de novo mutations in kinesin family member 2a (KIF2A) represent a significant cause of lissencephaly, microcephaly, and DRE." (PMID 34404749, 2021). "Four recently reported KIF2A-mutated human pediatric patients with MCD display band heterotopia, posterior predominant pachygyria, a thin corpus callosum, severe congenital microcephaly, and neonatal-onset seizures." (PMID 29313800, 2018). "Patients with missense mutations in KIF2A exhibit so called cortical dysplasia complex with other brain malformations (CDCBM), a type of MCD characterized by posterior agyria/pachygyria, microcephaly and severe motor dysfunction; and most of them suffer childhood epilepsy." (PMID 36733270, 2022).
lung adenocarcinoma (6 papers, 2019 to 2022). A carcinoma that arises from the lung and is characterized by the presence of malignant glandular epithelial cells. "Clinically, KIF2A could serve as a potential prognostic biomarker for facilitate prognostication of lung adenocarcinoma and esophageal squamous cell carcinoma patients." (PMID 35313389, 2022). "Furthermore, some in vitro experiments have shown that KIF2A functions as a tumor oncogene in several cancer cell lines (such as human malignant glioma, lung adenocarcinoma, and squamous cell carcinoma of the oral tongue)." (PMID 33331418, 2020). "In lung adenocarcinoma, high KIF2A expression could regulate metastasis by affecting the PI3K/AKT and MAPK/ERK signaling pathways." (PMID 30813560, 2019). "Moreover, silencing KIF2A reduces cell proliferation and migration, enhances cell apoptosis, and induces G2/M phase arrest through inhibiting PI3K/AKT and MAPK/ERK pathways in lung adenocarcinoma cells." (PMID 33331418, 2020).
lung carcinoma (5 papers, 2019 to 2025). "KIF2A expression is also clinically relevant, being associated with multiple prognostic factors in lung cancer patients." (PMID 40002279, 2025). "Functional studies in lung cancer models have implicated KIF2A in regulating multiple oncogenic phenotypes." (PMID 40002279, 2025). "KIF2A was also shown to influence lung cancer response to chemotherapy, as knockdown sensitized A549, H1975, and H1299 cells to cisplatin and paclitaxel, while overexpression conferred resistance to cisplatin." (PMID 40002279, 2025). "New research has shown that miR-338-3p suppresses the metastasis of lung cancer by influencing the MAPK signaling pathway or targeting KIF2A." (PMID 35992856, 2022). "In addition, the expression of KIF2A in lung cancer cells also increased significantly." (PMID 36447525, 2022). "In lung cancers (LUSQ and LUAD), aberrantly expressed KIF2A may serve as a valuable prognosis marker and candidate for therapeutic targeting." (PMID 30813343, 2019).